MTOR (mechanistic target of rapamycin kinase)
Diseases named in the same sentence as MTOR in open-access papers (continued):
Sharing a sentence is not in itself a finding about the gene and the disease.
lupus (110 papers, 2008 to 2026). "mTORC1 was activated in the B cells of lupus-prone mice, and rapamycin inhibited B lymphocyte proliferation and survival, indicating that mTOR is associated with pathogenic autoantibody production." (PMID 35050162, 2022). "ROS interferes with mTOR signaling to promote T cell overactivation in lupus, suggesting that ROS plays a pathogenic role in SLE development." (PMID 35296076, 2022). "CD4+ T cells from lupus patients show enhanced levels of mTOR activation which has been mechanistically linked with the disease process." (PMID 33968025, 2021). "As recently addressed, mTOR pathway activation is also implicated in autoimmune diseases such as systemic lupus erythematosus (SLE), which represents a prominent cause of seizures." (PMID 32121250, 2020). "Recent investigations demonstrated that abnormal mTOR activity was associated with the pathogenesis of inflammatory rheumatic diseases and autoimmune diseases, including rheumatoid arthritis, systemic lupus erythematosus and systemic sclerosis 31,32." (PMID 32922169, 2020). "It’s well known that the mammalian target of rapamycin (mTOR) exerts a critical role in the regulator of immune cells and is associated with T cells dysfunction in patients with systemic lupus erythematosus (SLE)." (PMID 33597869, 2020). "In vitro rapamycin treatment of human BMSC from lupus patients also reversed many of the abnormalities associated with cellular senescence including activation of the mTOR pathway, SABG expression, and cellular hypertrophy." (PMID 30637490, 2019). "Activation of mTOR occurs in T cells and other cell types in lupus and is responsible for multiple pathogenic processes." (PMID 30545086, 2018). "In systemic lupus erythematosus, oxidative stress can cause mammalian target of rapamycin (mTOR) activation, and this mTOR activation in turn is suggested to stimulate TH17 cell differentiation." (PMID 29201026, 2017). "To assess the significance of the association between human lupus genes and the mTOR pathway, we built an mTOR pathway interactome (ie, a network consisting of proteins that interact with the mTOR pathway) using IPA." (PMID 18980674, 2008). "In additional to preventing nephritis, sirolimus also had striking effects on the anti-DNA antibody titres in mice with lupus, so we addressed the connectivity of genes linked to any form of lupus with the mTOR pathway." (PMID 18980674, 2008). "We therefore posed the question: Of the genes linked to lupus in the published literature, how many can be placed in the rapalog-mTOR pathway?" (PMID 18980674, 2008). "The genes in the mTOR pathway interactome that are associated with lupus are, in large part, distinct from the genes involved in the other non-cancer diseases." (PMID 18980674, 2008). "About 50% of the lupus genes curated as lupus disease genes from human and rodent species in Ingenuity and MetaCore can be linked to the rapalog-mTOR pathway." (PMID 18980674, 2008). "In order to assess the likelihood of mTOR pathway involvement in human lupus, we examined the concordance between the mTOR pathway interactome and genes linked to human lupus and report the results of this analysis here." (PMID 18980674, 2008). "Therefore, understanding the mechanisms underlying the persistent MHP that leads to mTOR activation and enhanced Ca2+ flux is fundamental to understanding the pathogenesis of lupus." (PMID 27597882, 2016). "We constructed the mTOR pathway interactome consisting of proteins that interact with members of the mTOR pathway and identified a strong association between mTOR pathway genes and genes reported in the literature as being involved in human lupus." (PMID 18980674, 2008). "Autoimmune conditions such as systemic lupus erythematosus (SLE) are associated with elevated mTOR signaling." (PMID 40933955, 2025). "Therefore, we hypothesized that endothelial function in lupus mice would be impaired due to mTOR-associated decreases in nitric oxide signaling and reduced mitophagy." (PMID 39234308, 2024).
lupus (continued). "mTOR is also implicated in the pathogenesis of SLE, especially because systemic rapamycin administration alleviates lupus symptoms." (PMID 32849532, 2020). "Indeed, the MTOR pathway plays multiple roles in immunity, especially in the activation and proliferation of T cells, and has been implicated in the etiology of autoimmune disorders, such as systemic lupus erythematosus (SLE)." (PMID 21060808, 2010). "The direct involvement of EPS-TLR2 binding and PI3K/Akt/mTOR activation in Treg amplification in lupus models remains to be fully demonstrated." (PMID 40534849, 2025). "This medication, which is well-tolerated, has been demonstrated to reduce anti-DNA production and lupus activity via the suppression of mTOR." (PMID 40227251, 2025). "mTOR, a sensor of oxidative stress in lupus T cells, has been identified as a promising therapeutic target for rapamycin." (PMID 40227251, 2025). "Here, we identify a functional role for Rab4A-directed endosome traffic in CD98 receptor recycling, mTOR activation, and accumulation of mitochondria that connect metabolic pathways with immune cell lineage development and lupus pathogenesis." (PMID 38519468, 2024). "The current study's findings show that C. cicadae can alleviate renal fibrosis damage in lupus mice by targeting the phosphatidylinositol 3‐kinase (PI3K)/mammalian target of rapamycin (mTOR)‐mediated autophagy pathway." (PMID 38270299, 2024). "The overexpression of Rab4A preceded mTOR activation in several spontaneously lupus-prone mouse strains, including B6.TC, NZB/WF1, MRL, lpr, and MRL/lpr mice." (PMID 38519468, 2024). "Metformin application reduced M-MDSC differentiation via the AMPK/mTOR signal pathway signal and attenuated lupus symptoms in pristane-induced lupus mice." (PMID 37733169, 2024). "Our results from female lupus-prone mice (MRL/lpr) showed higher activation of mTOR in the liver and thoracic aorta." (PMID 39234308, 2024). "Inhibiting mTOR with rapamycin prevented endothelial dysfunction, attenuated lupus disease phenotypes and altered mitophagy markers in lupus mice." (PMID 39234308, 2024). "By exploring its regulatory effects on the PI3K/mTOR‐mediated autophagy pathway, we hoped to reveal the mechanism by which C. cicadae can repair renal fibrosis in mice with lupus and provide new strategies for clinical treatments." (PMID 38270299, 2024). "In conclusion, the present research identified a potential anti‐inflammatory, antioxidant, and antifibrotic role for C. cicadae in protecting against lupus‐induced renal impairment through the regulation of the PI3K/mTOR‐mediated autophagy pathway." (PMID 38270299, 2024). "Rapamycin forms a high-affinity complex with its cellular receptor FKBP12, which is overexpressed in lupus T cells, thereby blocking mTOR activation to improved disease activity in SLE patients." (PMID 39569194, 2024). "In T-cells of lupus patients and mice, elevated mTOR activity contributes to the pathogenesis of disease." (PMID 39234308, 2024). "Phosphorylation of mTOR from the liver was significantly higher in lupus mice (lpr_Control, 1.76 ± 0.21 a.u.)compared to the healthy control group (MpJ_Control, 1.00 ± 0.01 a.u.)(p = 0.01)." (PMID 39234308, 2024). "Rapamycin increases Drp1 through mTOR inhibition in lupus-prone mice and decreases mitochondrial dysfunction by activating mitophagy." (PMID 37894915, 2023). "In lupus-prone mice, mTORC1 is overexpressed in B cells, enhancing plasma cell differentiation and autoantibody production, while mTOR pathway inhibition by rapamycin decreased B-cell proliferation and survival." (PMID 37554724, 2023). "Here, we show that NCF1-dependent ROS at a physiological level limit development of pDCs in lupus through inhibition of the AKT/mTOR signaling." (PMID 36853827, 2023). "The mTOR inhibitor sirolimus has shown remarkable clinical efficacy in autoimmune diseases such as systemic lupus erythematosus and multiple sclerosis." (PMID 37360358, 2023).
lupus (continued). "The authors further demonstrated that miR-183 exhibited a protective effect on lupus via targeting mammalian target of rapamycin (mTOR) since there was reduced mTOR expression and activation in miR-183 mimic-treated cells." (PMID 36891312, 2023). "Metabolic changes impacting DNA methylation/demethylation have been reported in lupus patients and mTOR implications are also reported to be involved in SLE patients." (PMID 36743677, 2022). "This dose of NAC reduced the SLEDAI (SLE Disease Activity Index) score and the BILAG (British Isles Lupus Assessment Group) score and profoundly reduced mTOR activity in T lymphocytes." (PMID 36312742, 2022). "The medical researchers have also tried to treat lupus by inhibiting type I IFNs in a variety of ways, such as glucocorticoids, nicotinamide riboside and mTOR inhibitor." (PMID 36046235, 2022). "In contrast, Rab4 inhibited with 3-pyridinyl ethylidene hydroxyl phosphonocarboxylate (3-PEHPC) restores Drp1 function via the mTOR-independent pathway, reversing mitochondrial accumulation in lupus T cells." (PMID 35958572, 2022). "Lupus-prone mice treated with mTOR inhibitors showed a reduction in B cells differentiation into germinal centers and plasma cells, and lower disease activity." (PMID 35371016, 2022). "Metabolic regulation has been shown to be effective in a lupus mouse model and PBMCs from lupus patients to alleviate symptoms through an mTOR and NLRP3 regulation effect." (PMID 36743677, 2022). "Tryptophan and its metabolites increase T cell metabolism and mTOR activation, and Kyn promotes IFN-γ production, all of which are associated with the development of lupus in mice." (PMID 36110860, 2022). "Lupus is characterized by a depleted glutathione level, which regulates mammalian target of rapamycin (mTOR) in lupus T cells." (PMID 34239993, 2021). "mTOR inhibits the development of CD4+CD25+forkhead box P3(FoxP3)+ regulatory T cells (Tregs), which are deficient in lupus patients." (PMID 34239993, 2021). "Rapamycin (100-500 nM) inhibited mTOR over-activation and senescence in the BM-MSCs of patients with systemic lupus erythematosus." (PMID 34712416, 2021). "The findings revealed a novel mechanism linking IRF-8/miR-451a to M-MDSC differentiation via the AMPK/mTOR signal pathway during lupus development." (PMID 34282122, 2021). "Recent studies manifested that mTOR inhibitor rapamycin improved mitochondrial dysfunction via lupus-prone mice and inhibits apoptosis by activating mitophagy in spinal ischemia–reperfusion injury." (PMID 35757387, 2021). "RT-PCR and western blot analyses showed that the lupus group had lower miR-20a expression and higher Akt/mTOR phosphorylation levels compared to the normal group." (PMID 34721589, 2021). "Meanwhile, we found that MDSCs induced podocyte injury by increasing ROS in lupus nephritis and mammalian target of rapamycin (mTOR) inhibitor INK128 relieved the symptoms of pristane-induced lupus via downregulating the expansion of MDSCs." (PMID 34480018, 2021). "In our study, we found that miR-20a-ADSC and ADSC treatment inhibited the phosphorylation levels of Akt and mTOR through miR-20a in the kidney of mouse lupus models." (PMID 34721589, 2021). "Recently, the agonist for AMPK (upstream molecule of mTOR signal), metformin, was reported to relieve lupus symptoms by regulating abnormal T and B cells." (PMID 34282122, 2021). "ADSC and miR-20a-ADSC treatment resulted in the upregulated expression of miR-20a and inhibited the phosphorylation of Akt and mTOR compared with the lupus group, and the miR-20a group had a much stronger effect compared with the ADSC group (all P < 0.05)." (PMID 34721589, 2021). "Drugs for treating systemic lupus erythematosus, such as glucocorticoids, hydroxychloroquine, and sirolimus, all belong to mTOR inhibitors, which have beneficial effects." (PMID 34722413, 2021).
lupus (continued). "Rapamycin increases Drp1 via mTOR inhibition in lupus-prone mice and decreases mitochondrial dysfunction by activating mitophagy." (PMID 32903665, 2020). "As expected, the mammalian target of rapamycin (mTOR), a sensor of the mitochondrial transmembrane potential and ROS supply, is activated in lupus T cells." (PMID 32477606, 2020). "Inhibition of glycolysis, lipid synthesis, and mTOR signaling can control inflammation and alleviate disease activity in lupus mouse and SLE patients." (PMID 32528480, 2020). "The mTOR inhibitor rapamycin has already been shown to be beneficial for disease activity in murine models of lupus." (PMID 30637490, 2019). "In support of sirolimus as a suitable treatment option in SLE, blockade of the mTOR pathway has shown promising effects in lupus animal models as well as in patients." (PMID 30787878, 2019). "N-acetylcysteine (NAC), a well-known antioxidant, has been reported to inhibit mTOR in vitro and improve the outcome of murine lupus and even SLE patients." (PMID 31016198, 2019). "Recent studies have suggested that the addition of N-acetyl L-cysteine (NAC), which helps to replenish intracellular glutathione, decreases lupus through blocking mTOR." (PMID 30545086, 2018). "Rapamycin, a specific mTOR inhibitor, can effectively decrease lupus disease in both lupus-prone mice and patients." (PMID 30545086, 2018). "Rapamycin treatment restored Treg function, indicating that mTOR signaling in Tregs constitutes a potential checkpoint in lupus pathogenesis." (PMID 30563559, 2018). "mTOR signaling is important in enhancement of humoral immune responses, and an mTORC1 inhibitor ameliorates lupus pathologies." (PMID 29963056, 2018). "A recently completed clinical trial showed that blocking mTOR activation with rapamycin in lupus patients reduced disease activity, including arthritis." (PMID 30233578, 2018). "A randomized, double-blind, placebo-controlled study has proved that N-acetylcysteine reduces disease activity by blocking mTOR pathway in T cells from systemic lupus erythematosus patients." (PMID 27597882, 2016). "As such, deregulation of mTOR can facilitate T-dependent autoimmune disorders like systemic lupus erythematosus and multiple sclerosis." (PMID 26496200, 2015). "The PPP-connected and NAC-responsive accumulation of kynurenine and its stimulation of mTOR are identified as novel metabolic checkpoints in lupus pathogenesis." (PMID 26366134, 2015). "Oxidative stress induces nitric oxide activity and elevation of mitochondrial transmembrane potential which lead to activation of the protein kinase named mitochondrial transmembrane potential and mammalian target of rapamycin (mTOR) in lupus T cells." (PMID 24864268, 2014). "Overexpression of HRES-1/Rab4 and activation of mTOR can be detected in T cells of patients with systemic lupus erythematosus (SLE) and lupus-prone mice, where autophagy appears to be involved in disease pathogenesis." (PMID 24404161, 2014). "Blockade of mTOR with rapamycin, which is an effective treatment in patients with systemic lupus erythematosus, inhibited the oxidative stress-induced expression of HRES-1/Rab4 and the lysosomal degradation of CD4 and CD3ζ." (PMID 24404161, 2014). "Rapamycin, an inhibitor of mTOR, was demonstrated in a small clinical study of nine lupus patients to be able to normalize T-cell activation-induced calcium influx and reduce overall lupus disease activity." (PMID 24864268, 2014). "Increase in mTOR activity causes RAB4A-mediated CD3ζ downregulation and results in high calcium flux when lupus T cells are stimulated." (PMID 24864268, 2014). "Using curated findings in IPA, at least 50% of the known lupus-associated genes in IPA and Metacore interact with components of the rapalog-mTOR pathway." (PMID 18980674, 2008).
lupus (continued). "In CD4+ T cells from SLE patients or lupus-prone mice, activation of the mTOR signaling pathway drives enhanced glycolysis, which promotes the differentiation of CD4+ T cells into pathogenic Th17 cells while compromising the immunosuppressive function of Treg cells." (PMID 40655145, 2025). "L. casei and L. reuteri also enhance antioxidant enzyme activities such as glutathione peroxidase, suppressing oxidative stress and stabilizing regulatory T cells by preventing ROS-dependent mTOR activation, which plays a role in immune regulation in lupus models." (PMID 40534849, 2025). "In lupus T-cells, mitochondrial dysfunction including mitochondrial hyperpolarization, mitochondrial accumulation, and impaired mitophagy is mediated by increased Rab4A and its interaction with mTOR." (PMID 39234308, 2024). "mTOR activity is also elevated in renal endothelial cells of lupus patients and mice and could serve as a biomarker and predictor of disease progress in lupus nephritis." (PMID 39234308, 2024). "Activation of the mechanistic target of rapamycin (mTOR) is a key metabolic checkpoint of pro-inflammatory T-cell development that contributes to the pathogenesis of autoimmune diseases, such as systemic lupus erythematosus (SLE), however, the underlying mechanisms remain poorly understood." (PMID 38519468, 2024). "Taken together, low ROS production due to NCF1 deficiency enhances AKT/mTOR-dependent pDC generation and promotes pDC migration via CCR2, which may explain the accumulation of pDCs during lupus." (PMID 36853827, 2023). "Additionally, the mTOR inhibitor “sirolimus”, as well as the calcineurin inhibitor “tacrolimus”, were recognized as potent modulators of the lupus monocyte gene signature." (PMID 37072752, 2023). "Our previous studies found that the activation of mTOR, a key kinase in cellular metabolisms, could mediate MDSCs to induce the unbalance of Th17/Treg in lupus mice." (PMID 36746935, 2023). "Our previous study found that the activation of mammalian target of rapamycin (mTOR), a key kinase in cellular metabolisms, could mediate MDSCs to induce the unbalance of Th17/Treg in lupus mice." (PMID 36746935, 2023). "The ameliorating effect of mTOR inhibition on lupus has been well documented." (PMID 36891312, 2023). "Moreover, the mTOR signaling pathway is regulated by IGFBP2 in cancer; we next examined the effect on AKT/mTOR signaling pathway with IGFBP2 blockade in mouse models of lupus." (PMID 36008635, 2022). "Similarly, the highly expressed mammalian target of rapamycin (mTOR) in lupus mice has also been shown to induce lupus nephritis (LN) through activation of mTOR/mitochondrial ROS/NLRP3 signaling." (PMID 35693810, 2022). "In addition, and similar to studies in humans, the mTOR inhibitor rapamycin was capable to restore T cell metabolism and to decrease disease activity in lupus-prone MRL/lpr mice." (PMID 36389689, 2022). "The present study explored the treatment mechanism of metformin and found that metformin attenuated lupus symptoms by regulating the differentiation of M-MDSCs, and the percentage of M-MDSCs decreased by inhibiting the AMPK/mTOR signal pathway in vitro and in mice with pristane-induced lupus." (PMID 34282122, 2021). "A previous study found that mTOR inhibition could attenuate lupus symptoms by regulating the differentiation and functions of total CD11b+Gr1+ MDSCs." (PMID 34282122, 2021). "Moreover, myeloid-derived CD11b+Gr1+ cells were confirmed to increase prior to abnormal changes in T and B cells during pristane-induced lupus development, and the mTOR pathway was critical for MDSCs in lupus development." (PMID 34282122, 2021). "It is therefore plausible that mTOR inhibition may represent a promising novel approach in the treatment of patients with lupus." (PMID 33748165, 2021). "In the T lymphocytes of patients with systemic lupus erythematosus, the mTOR pathway is activated." (PMID 34722413, 2021).